IL6 (interleukin 6)
Diseases named in the same sentence as IL6 in open-access papers (continued):
Sharing a sentence is not in itself a finding about the gene and the disease.
sarcopenia (continued). "Sarcopenia subjects were older and had higher visceral fat tissue (VFA) than non-sarcopenia subjects (P < 0.05), along with higher IL-6 and IL-10 levels." (PMID 30541467, 2018). "Among the candidates investigated, serum levels of IL-6, SPARC, MIF and IGF-1 were significantly different between normal and sarcopenia groups, but not the other biomarkers (data not shown)." (PMID 29872072, 2018). "Third, specific pro-inflammatory cytokines such as IL-6, TNF-α, and IL-1β–known to play direct roles in the pathogenesis of sarcopenia—were not available in the NHANES dataset and, thus could not be analyzed." (PMID 40708651, 2025). "In fact, a recent meta-analysis of 17 cross-sectional studies involving a total of 11,249 participants confirmed that those with sarcopenia had significantly higher CRP levels than those without, while serum IL-6 levels and TNF-α were comparable in both groups." (PMID 36291982, 2022). "Proinflammatory cytokines, such as IL-6 and TNF-α, induce the production of CRP in the liver, and it has not been clarified whether high CRP level directly affects sarcopenia." (PMID 29259690, 2016).
coronary artery disease (477 papers, 2005 to 2026). "Specifically, CTRP2 expression has been shown to reduce oxidative stress, inhibit cytokine production such as TNF-α and IL-6 and has been linked to a number of inflammatory associated disease states (e.g., Coronary Artery Disease)." (PMID 40143094, 2025). "A 2024 study aimed to establish a risk prediction model of coronary heart disease in SjD based on IL-6 levels and regulatory T cell percentages." (PMID 41002646, 2025). "In the REPRIEVE (Reinforced Vascular Event Prevention in HIV) randomized trial, coronary artery disease detected by computed tomography was independently associated with IL-6 levels in PLWH." (PMID 40718411, 2025). "First, chronic inflammation associated with coronary heart disease, driven by elevated cytokines such as interleukin-6 (IL-6) and tumor necrosis factor-alpha (TNF-α), accelerates bone resorption by activating osteoclasts." (PMID 40921881, 2025). "The association with AAA was of greater magnitude than associations with coronary artery disease and even rheumatological disorders for which IL6 inhibitors have been approved." (PMID 39633572, 2025). "While hsCRP is as a downstream marker of inflammation with no causal involvement, Mendelian randomization studies support a causal role of IL-6 signaling in the development of HF and coronary artery disease." (PMID 41196450, 2025). "Ultimately, this study identified ESR (OR 1.10, p = 0.019), triglyceride levels (OR 3.67, p = 0.041), IL-6 (OR 1,29, p = 0.048) and regulatory T cell percentage (OR = 0.25, p = 0.004) as independent risk factors for coronary heart disease in SjD patients." (PMID 41002646, 2025). "Further, interleukin-6 (IL-6), a pleiotropic pro-inflammatory cytokine, has been linked withendothelial dysfunction, plaque instability, and poor prognosis in both AF and coronary artery disease patients." (PMID 40978648, 2025). "Mendelian randomization studies have suggested a driving role for IL-6 signaling in the development of coronary artery disease, a common underlying etiology of HF." (PMID 41196450, 2025). "In patients with coronary artery disease, platelet activation is linked to elevated levels of inflammatory cytokines such as IL-1β, IL-6, and TNF-α." (PMID 40807011, 2025). "The GG genotype is associated with a decreased risk for developing some cancers and it is associated with low levels of IL-6 amongst patients with coronary artery diseases." (PMID 38783228, 2024). "IL6 is an inflammatory marker with an important connection with coronary artery disease and the risk of HF." (PMID 38786964, 2024). "MR analysis, utilizing rs2228145 as the sole instrumental variable, has demonstrated that attenuated IL-6 signaling can mitigate the risk of coronary artery disease." (PMID 39229261, 2024). "Coronary artery disease is associated with increased levels of proinflammatory cytokines such as IL-1β, IL-6, interferon-γ (IFN-γ), and TNF-α." (PMID 38267838, 2024). "Consistent with these previous studies, we found that advanced age, pre-existing coronary artery disease, interleukin-6, and procalcitonin remain high-risk factors for the occurrence of myocardial injury in elderly patients infected with the Omicron variant." (PMID 38420262, 2024). "AF is remarkably associated with elevated IL-6 in the patients with coronary artery disease, chronic obstructive pulmonary disease, chronic kidney diseases, and many other systemic inflammatory diseases." (PMID 38889387, 2024). "IL-6, linked to myocardial fibrosis and remodeling, has been implicated in dilated cardiomyopathy, yet its connection to ischemic heart disease is scant." (PMID 38935941, 2024). "Here, we show that IL-6 is associated with increased progression of both total and noncalcified plaque burden among asymptomatic patients with stable coronary artery disease." (PMID 39304297, 2024).
coronary artery disease (continued). "Most previous studies focused on IL-6 and demonstrated that IL-6 is associated with AF in post-menopausal women, patients with stable coronary artery disease, in individuals following coronary artery bypass surgery, and in patients with chronic kidney disease." (PMID 39202519, 2024). "Interleukin-6 (IL-6) is an important proinflammatory cytokine genetically linked to coronary artery disease." (PMID 38525188, 2024). "It has been established that elevated levels of IL-6 are related to an increased risk of coronary heart disease, and it is believed to play a crucial role in the onset and progression of the inflammatory process that leads to coronary plaque formation." (PMID 38525188, 2024). "Interleukin-6 (IL-6), a pro-inflammatory cytokine, has been proposed as a potential predictor of coronary artery disease (CAD) severity and has been associated with plaque burden, as assessed by intracoronary imaging." (PMID 38218768, 2024). "Plasma IL-6 levels are significantly associated with increased total and noncalcified short-term plaque progression in patients with stable coronary artery disease." (PMID 39304297, 2024). "Consistently, prior studies also reported that genetically determined lower IL-6 level was associated with a decreased risk of coronary heart disease events." (PMID 38589871, 2024). "Previous studies have investigated cytokine gene promoter methylation patterns and their relation to CVDs, namely IL-6, a cytokine that is involved in pro-inflammatory processes underlying the development of coronary heart disease." (PMID 38132456, 2023). "Genotyping for the IL-6 gene has revealed that IL-6 polymorphism is independently associated with coronary artery disease." (PMID 37996879, 2023). "For example, coronary artery disease is associated with higher expression of interleukin (IL)-6, a cytokine present during the acute inflammatory phase, on Mon236." (PMID 36593308, 2023). "Genetic studies broadly show a causal association between IL-6 and the development of coronary artery disease." (PMID 37175639, 2023). "IL-6 baseline levels were associated with an increased risk of developing coronary heart disease at the end of the follow-up period." (PMID 37629496, 2023). "In human, some studies reported the association between peripheral Th1/Th2 ratio or plasma IL-6 levels and the severity of coronary artery disease but the inflammatory response has been less characterized." (PMID 37798364, 2023). "IL-6 has been implicated in the pathology of a wide range of diseases, including coronary artery disease (CAD), which contributes to diabetes, aging and cancer progression." (PMID 36296903, 2022). "Elevated IL-6 concentrations have been linked to multiple clinical parameters (e.g., blood pressure, insulin sensitivity and coronary artery disease)." (PMID 35352134, 2022). "Another study reported that reduced IL-6 gene methylation was associated with higher IL-6 plasma levels in ischemic heart disease patients." (PMID 36551003, 2022). "Increased circulating IL-6 levels are associated with coronary artery disease, promote vascular inflammation, and increase circulating CRP levels." (PMID 36012889, 2022). "Based on the relationship between its serum levels and coronary heart disease events, several studies noted a direct association between serum IL-6 and the risk or severity of coronary heart disease." (PMID 35884067, 2022). "It has been reported that high circulating concentration of IL-6 is associated with increased risk of coronary heart disease in prospective observational studies." (PMID 36060677, 2022). "The present study shows that serum IL-6 is predictive of long-term cardiovascular events in symptomatic patients with stable coronary disease who have a high cardiovascular risk." (PMID 36028849, 2022). "Based on genetic studies, interleukin 6 (IL-6) appears to have a causal role in coronary heart disease." (PMID 35837017, 2022).
coronary artery disease (continued). "Blocking the expression of IL-6 or its receptor to the perturb IL-6 signaling pathway results in a reduction in the risk of coronary artery disease and atrial fibrillation, as well as T2D." (PMID 36141228, 2022). "A recent meta-analysis examined more than 40 studies related to rs1800795, with the firm conclusion that there is a clear association with coronary artery disease driven, at least in part, by upregulating plasma IL-6 levels." (PMID 36337884, 2022). "IL-6 has also been associated with the progression of carotid artery stenosis and coronary artery disease in high-risk groups." (PMID 36013196, 2022). "Recently, a study suggested that IL-6 levels were elevated in 69 coronary artery disease patients with TCFAs and high-risk plaques, as defined by OCT and intravascular ultrasound." (PMID 36555579, 2022). "A prior study pointed out that IL-6 was a positive feedback factor, which caused the aging mitochondrial dysfunction in coronary artery diseases." (PMID 34222381, 2021). "Due to the short half-life and high variability of Interleukin-6 (IL-6), limited studies have been performed on the association of serum levels of interleukin-6 with coronary artery disease." (PMID 33436103, 2021). "Meta-analysis of human studies has shown that long-term elevation of IL-6 more than doubles a person's lifetime risk of coronary heart disease." (PMID 34179145, 2021). "Circulating IL-6 levels and at least one polymorphic form of IL6 gene have been reported to be independently associated with coronary artery disease (CAD), at least amongst Caucasians." (PMID 34595552, 2021). "Most notably, elevated CRP and IL6 levels have been found to be associated with increased risk of coronary heart disease events in many large prospective observational studies." (PMID 34168680, 2021). "DNA hypomethylation in the IL-6 promoter was associated with an increased risk for coronary heart disease, especially in acute myocardial infarction." (PMID 34576113, 2021). "IL-1 strongly induces Interleukin-6 (IL-6) and has been attributed a causal role in human coronary heart disease." (PMID 35087883, 2021). "The aim of this study is to investigate the relationship between IL-6 gene polymorphisms and coronary artery disease." (PMID 33436103, 2021). "In this study, the relationship between IL-6 gene polymorphism and coronary artery disease is examined." (PMID 33436103, 2021). "IL-6 levels are closely linked to the extent of coronary artery disease in ACS patients undergoing percutaneous coronary intervention." (PMID 34861824, 2021). "Studies also reported that IL-6 and IL-8 are associated with multiple cardiovascular diseases, such as coronary artery disease, atherosclerosis, sudden cardiac death." (PMID 33254709, 2020). "Long-standing elevation of levels of C-reactive protein, interleukin 6 (IL-6), activated protein C is now widely considered independent risk factors for coronary artery disease." (PMID 33062549, 2020). "As an important pro‐inflammatory cytokine, IL‐6 has been proven to be an independent risk factor for coronary artery disease and is expressed at relatively high levels in human atherosclerotic plaques." (PMID 32374489, 2020). "Studies examining the associations between the interleukin‐6 (IL‐6) rs1800795 and rs1800796 gene polymorphisms and risk of coronary artery disease (CAD) remain controversial." (PMID 32374489, 2020). "The study found that increased serum SP-D was associated with total mortality in patients with documented coronary artery disease also when adjusting for well-established risk factors such as smoking, age, sex, plasma cholesterol, and plasma IL-6 levels." (PMID 31616435, 2019). "Clinical studies revealed that high levels of serum IL-6 represent a risk factor for coronary artery disease." (PMID 32082145, 2019).
coronary artery disease (continued). "NFKBIA polymorphisms modulated the risk of coronary artery disease in the Chinese Uygur population by regulating various cytokines including interleukin-6, which is a key mediator of the inflammatory process and atherosclerotic plaque formation." (PMID 31180540, 2019). "IL-6 released by NK cells has been shown to be an early event in SSc associated with SSc onset and IL-6 secretion was demonstrated to be correlated with EMPs release and vascular inflammation associated with coronary disease." (PMID 30072999, 2018). "Previous studies have observed the association between IL-6 gene polymorphisms and coronary artery disease." (PMID 28878828, 2017). "We aimed to evaluate the relationship between IL-6-174G>C, -572G>C and -597G>A polymorphisms and development of coronary artery diseases in a Chinese population." (PMID 27648032, 2016). "This study suggests that IL-6 -592G>C polymorphism is correlated with the risk of coronary artery disease." (PMID 27648032, 2016). "IL-6 trans-signaling is also an independent risk factor for coronary artery disease and is involved in inflammatory processes in vessels." (PMID 27801847, 2016). "The relationship between IL-6-174G>C, -592G>C and -597G>A polymorphisms and development of coronary artery diseases is described in Table-IV." (PMID 27648032, 2016). "For instance, a recent large-scale human genetic study suggested that interleukin-6 (IL-6) signaling pathway is causally related to coronary heart disease." (PMID 25722960, 2015). "A causal role for IL-6 signaling in coronary heart disease is still elusive, but has been considered." (PMID 26100072, 2015). "Individuals with increased risk for coronary artery disease presented reduced interleukin-1 (IL-1), IL-6, TNF-α, and C-reactive levels, together with improved IL-10 and transforming growth factor beta-1 systemic levels after an ET program." (PMID 25045207, 2014). "IL-6 is a key mediator of inflammation and as such has been implicated in the pathogenesis of atherosclerosis and coronary artery disease (CAD)." (PMID 25516764, 2014). "Increased levels of IL-6 were found in coronary heart disease patients and were associated with prognosis." (PMID 25032959, 2014). "This cytokine is up-regulated in vulnerable atherosclerotic lesions and higher levels of serum IL-6 are associated with an increased risk of coronary heart disease." (PMID 24391744, 2013). "A meta-analysis of prospective studies involving white populations confirmed that polymorphisms of the IL-6 gene were also associated with the development of coronary artery diseases." (PMID 24244750, 2013). "The level of hs-CRP (1.0 mg/L) or IL-6 (≥1.5 pg/mL) was used as a cut-off point to define higher inflammation status, which is an average risk factor for coronary artery disease." (PMID 23029185, 2012). "Studies of the −174G>C polymorphism in IL-6 gene and risk of coronary heart disease under additive model grouped by study characteristics." (PMID 22509361, 2012). "ORs and 95% CI for coronary heart disease and the −174G>C, −572 G>C polymorphism in IL-6 gene under various genetic models." (PMID 22509361, 2012). "A high circulating concentration of interleukin 6 is associated with increased risk of coronary heart disease." (PMID 22421340, 2012). "Studies of the −572 G>C polymorphism in IL-6 gene and risk of coronary heart disease under additive model grouped by study characteristics." (PMID 22509361, 2012). "We have examined the contribution of the -174G>C IL-6 promoter variant on the risk of coronary artery disease (CAD) among Tunisians." (PMID 21245598, 2011). "The influence of interleukin-6 G-174C gene polymorphism on coronary artery disease, cardiovascular complications and mortality in dialysis patients was described in a previously reported study." (PMID 19804633, 2009).